AHR (aryl hydrocarbon receptor)
Diseases named in the same sentence as AHR in open-access papers (continued):
Sharing a sentence is not in itself a finding about the gene and the disease.
hepatoma (continued). "Alternatively, Gharavi and El-Kadi (2005) showed in murine hepatoma cell lines that Cyp1a1 is down-regulated by the proinflammatory cytokines interleukin 1β (Il-1β), IL-6, and tumor necrosis factor α in an AHR-dependent manner." (PMID 19165387, 2009). "In the present study, we combined multiple technologies and knowledge bases to conduct an integrative genomewide analysis of AHR gene targets in mouse hepatoma cells." (PMID 19654925, 2009). "Recent studies using DNA microarray techniques suggested that approximately 300 genes were altered by TCDD-dependent AhR activation in the human hepatoma HepG2 cells." (PMID 19936078, 2007). "For example, the unexpectedactivity of 1,4-cyclohexanedione in both hepatoma cells used for high-throughputscreening and in human keratinocytes adds to the possible ways suchchemicals could interact with and activate the AHR." (PMID 38598786, 2024). "To ensure that the results of the ligand-binding assay performed with mouse AhR did not compromise the results of the effect of jasmone on human AhR activity in the cell-based assay, we generated a stably transfected mouse hepatoma cell line (Hepa1c1c7 cells) responsive to AhR and named it Aherepa." (PMID 37958638, 2023). "Perioperative therapies using an AhR agonist to improve NK cell function may reduce the recurrence of hepatocellular carcinoma after hepatectomy." (PMID 37747052, 2023). "Human hepatoma cell line HepG2 has been extensively used as a model in assessing human health risks, as well as in investigating the effects of xenobiotics on the activation of AHR pathways." (PMID 37959792, 2023). "AhR factor stimulated the expression of HDAC8 via the AhR-ARNT complex in human hepatoma cells." (PMID 35987825, 2022). "Lack of the AhR has been shown to be associated with an impaired activation of Akt in mouse hepatoma cells." (PMID 36077780, 2022). "Aspergillus flavus was reported to be involved in the production of aflatoxin, targeting aryl hydrocarbon receptor to mediate the expression of P450 to induce hepatocellular carcinoma process, indicating that these species seemed to have an underestimated relation with colorectal cancer." (PMID 35281451, 2022). "We also provided experimental evidence to support the interaction between rutaecarpine and AhR in mouse hepatoma cells using the well-established DRE-driven reporter gene assay, as well as in human glioblastoma cells via determination of the classical AhR responsive gene CYP1B1." (PMID 34955744, 2021). "To demonstrate a requirement for ARNT in 1,2-NQ- and 1,4-NQ-dependent induction of AhR-responsive gene expression, we examined the ability of 1,2-NQ and 1,4-NQ to induce AhR-dependent reporter gene expression in wild-type (Hepa1c1c7) and ARNT-deficient (BPRc1) mouse hepatoma cells." (PMID 32526934, 2020). "Further, some quinones, including 1,2-NQ and 1,4-NQ, simulate AhR nuclear translocation and induction of cyp1a1 in mouse hepatoma cells in an AhR-dependent manner and the induction could be blocked by an AhR antagonist." (PMID 32526934, 2020). "The upregulation of FOXQ1 seems to be consistent with previous studies suggesting an AHR-dependent increase in the expression of this transcription factor either in rat hepatic progenitor cells or in a rat hepatoma cell line exposed to PCB126 and TCDD, respectively." (PMID 32610656, 2020). "Difeconazole induces the AHR target gene CYP1A1 in human hepatoma cells." (PMID 32403288, 2020). "These two toxins are AhR activators in mouse hepatoma cells." (PMID 31681212, 2019). "IS inhibited the expression of fetuin-A through AhR activation in a human hepatoma HepG2 cell line." (PMID 29543732, 2018). "In addition, we found that raloxifene and its analog Y134 inhibit hepatoma cells in an AhR dependent manner." (PMID 29194351, 2017).
hepatoma (continued). "AhR expression affected malignancy since liver carcinomas could be recovered from AhR−/− mice whereas adenomas were predominant in AhR+/+ mice." (PMID 28874739, 2017). "We further analyzed whether the AHR antagonist CH223191 could inhibit the ability of SU5416 to activate the DRE in 101L-hepatoma cells." (PMID 22970246, 2012). "Differences in AhR levels, co-activator availability, and protocols used in their isolation of these hepatoma cells may confound our comparisons." (PMID 21496263, 2011). "We conducted an integrative genomewide analysis of AHR gene targets in mouse hepatoma cells and determined whether AHR regulatory functions may take place in the absence of an exogenous ligand." (PMID 19654925, 2009). "Although in the absence of a ligand AhR promotes progression of the cell cycle as shown in mouse hepatoma Hepa1c1c7, AhR null MEF cells and HepG2 human hepatoma cells transfected with AhR siRNA, accumulating data strongly suggests that TCDD inhibits cell proliferation." (PMID 19531241, 2009). "Furthermore, we studied the potential effects of AhR on the phenotype of the mouse hepatoma cells, including cell cycle, morphology and the expression of albumin." (PMID 19936078, 2007). "In support of this hypothesis, AhR inhibition through molecular manipulations, such as transfection of AhR-specific siRNA, suppresses proliferation of human hepatoma cells while AhR-defective hepatoma cells grow more slowly than wild-type cells." (PMID 16569260, 2006). "AHR has emerged as a pivotal regulator of hepatic metabolic reprogramming, with roles in the development of metabolic dysfunction-associated fatty liver disease (MAFLD), that increases the risk for progression to end-stage liver disease, and hepatocellular carcinoma (HCC)." (PMID 41303339, 2025). "It is hypothesized that HCV infection may expedite the development of hepatocellular carcinoma (HCC) by amplifying the tryptophan (Trp)-TDO-Kyn-AhR pathway, thereby impeding immune responses against viral and tumor antigens, ultimately leading to tumorigenesis." (PMID 38680494, 2024). "We previously observed that suppression of the AHR levels after down-regulation of p23 in Hepa1c1c7 mouse hepatoma cells was caused by increased AHR degradation, which could not be reversed by the treatment of a proteasome inhibitor MG132." (PMID 32414129, 2020). "Also, the AhR activation was demonstrated when FB1 was evaluated in H4IIE hepatoma cells." (PMID 31681212, 2019). "In addition, analog E had better AhR-dependent effects in hepatoma cells compared to raloxifene." (PMID 29194351, 2017). "Also, it interacts with signaling pathways controlling cell adhesion and migration, indicating that AHR expression may activate hepatocellular carcinoma development, which is different from our findings." (PMID 29212263, 2017). "We selected three hepatocellular carcinoma cell lines (HepG2, Huh7, and SMMC-7721) that have enriched plasma unactivated AHR, as well as the human fetal hepatocyte line LO2." (PMID 40248203, 2025). "We also confirmed the interaction between AHR and SPHK2 using an additional cell line (Huh7, a human hepatoma cell line, and a different AHR agonist, indolo[3,2‐b] carbazole (ICZ)." (PMID 39207053, 2024). "Some studies show the overexpression of TDO in human hepatocellular carcinoma patient tissues that drives cell growth, migration, invasion, and epithelial to mesenchymal transition (EMT) via the AhR pathway." (PMID 38807762, 2024). "TCDD has been reported to induce PAI-1 gene expression through AhR- and ARNT-dependent mechanisms in mouse hepatoma cell lines." (PMID 39596044, 2024). "AhR has been proposed to activate the Akt/PI3K/mTOR axis, and AhR inhibition is thought to lower the PI3K functions and restore sensitivity to apoptosis, as observed in mouse-model hepatoma cell lines." (PMID 36982245, 2023).
hepatoma (continued). "In murine Hepa-1 hepatoma cells it was shown that ARNT and ARNT2 dimerize equally with the AHR in the presence of TCDD and that ARNT2 outcompetes ARNT for binding to the AHR when expressed in excess." (PMID 37696456, 2023). "Dexamethasone (DEX) increased AHR mRNA, protein, and TCDD-binding by approximately 50% in Hepa-1 mouse hepatoma cells, which was blocked by a GR antagonist." (PMID 37696456, 2023). "Do all cancer cells transfer 14-3-3zeta in exosomes to t cells in order to upregulate AANAT, which, when coupled to kynurenine activation of the AhR, increases the NAS/melatonin ratio, as indicated by data in hepatocellular carcinoma exosomes ?" (PMID 36613754, 2022). "The overall results indicated that the function of AHR was required for AFB1-induced cell death, which was confirmed in HuH7 hepatoma cells." (PMID 34373448, 2021). "In this study, we performed a systematic analysis of the potential of different PAHs to interact with the human nuclear receptors AHR and CAR and the subsequent regulation of their respective target genes in human hepatoma cell lines." (PMID 33396476, 2020). "Related reports revealed that most core DMEs were positively correlated with AHR, PXR and PPARα, and their protein expression was downregulated in nearly 50% of the patients with hepatocellular carcinoma (HCC)." (PMID 33240601, 2020). "Previous studies show that AhR can activate the Akt/PI3K/mTOR pathway, and AhR inhibition results in low PI3K activity and also restores sensitivity to apoptosis in the mouse hepatoma cell line." (PMID 30766532, 2019). "For example, while the AhR agonist indirubin (IR) has been shown to have a 10-fold greater potency as an inducer of AhR-dependent gene expression than TCDD in human hepatoma cells, it is ~10-fold less potent than TCDD in mouse hepatoma cells." (PMID 30201897, 2018). "In summary, we demonstrated that AHR regulated cell proliferation and tumorigenesis by directly targeting and activating HDAC8 expression in hepatoma cells." (PMID 27283490, 2017). "Our data showed that the induction of AHR activated cellular expression of HDAC8 and consequently suppressed RB1 expression in hepatoma cells." (PMID 27283490, 2017). "Forced AHR overexpression enhanced mRNA and protein expression of CYP1B1 and HDAC8 in both hepatoma cell lines." (PMID 27283490, 2017). "The hepatoma cells exhibiting both AHR and HDAC8 expression showed a more pronounced additive effect on transformation activity than that of AHR or HDAC8 alone." (PMID 27283490, 2017). "Due to our interest in developing AhR-targeted anti-cancer agents, we were intrigued by the anti-proliferative effects of SU5416 in hepatoma cells." (PMID 28424418, 2017). "Consistently, we found that Arnt was required for the effects of SU5416 in hepatoma cells, suggesting that SU5416 mediates its effects in Hepa1 cells via transcriptional activation of the AhR." (PMID 28424418, 2017). "Envisioning a potential repurposing of this molecule via the AhR in a responsive cancer, we sought to characterize the AhR-dependent functional effects of SU5416, focusing on its anti-proliferative effects in hepatoma." (PMID 28424418, 2017). "In studies using rats and human hepatoma cells, it has been found that ASA can block the AhR, preventing dioxins being transformed within the body and having negative effects." (PMID 27942866, 2017). "Δψm increased following activation of the aryl hydrocarbon receptor (AhR) by 2,3,7,8 tetrachlorodibenzo-p-dioxin (TCDD) in murine hepatoma Hepa1c1c7 cells." (PMID 27488617, 2016). "In rodent hepatoma cell models, TCDD treatment leads to AhR-dependent inhibition of G0/G1 to S-phase progression and accumulation of cells in G0/G1 phase of cell cycle." (PMID 27274734, 2016). "Exposure of hepatoma cells to TCDD led to induction of Nrf2 mRNA and protein, which was abolished by siRNA, targeted against AhR." (PMID 27829840, 2016).
hepatoma (continued). "Furthermore, in a mouse model of hepatocellular carcinoma, Kyn was shown to induce PD-1 upregulation in CD8+ T cells by activating the aryl hydrocarbon receptor (AhR), thereby evading immune killing and reducing the efficacy of immunotherapy." (PMID 41488615, 2025). "Moreover, together with the loss of growth arrest, the previous enhancement of maturation in the hepatoma line was significantly reduced as shown by decreased expression of maturation markers CYP3A4, ALB, AHR, GLUL, and PCK1." (PMID 38037844, 2024). "Studies on hepatocellular carcinoma have shown that the activation of AhR can have an oncogenic effect, as opposed to immune escape." (PMID 38434684, 2024). "Also in hepatocellular carcinoma patients, HDAC8 expression significantly correlated with AHR transcription and protein levels." (PMID 37696456, 2023). "The absence of AhR in mouse hepatoma cells or its knockdown in human hepatoblastoma cells leads to a delay in the G1 to S-phase transition." (PMID 36077780, 2022). "Recombinant human hepatoma (HG2L7.5c1) cells, which contain an AhR-responsive luciferase reporter plasmid under the control of 20 dioxin responsive elements (DREs), respond to AhR agonists with the induction of firefly luciferase in a time-, dose- and AhR-dependent manner." (PMID 35458697, 2022). "Specifically, studies in mouse hepatoma cells proved PB to be a weak ligand of AhR, as well as an inducer of CYP1A1 and benzo[a]pyrene hydroxylase activity; on the contrary, CYP1A2 was regulated through molecular mechanisms independent from AhR." (PMID 35408925, 2022). "Crosstalk between the AHR and hypoxia pathways was evident in a study, where endogenous AHR ligand suppressed nuclear accumulation of HIF2α and subsequent EPO production in human hepatoma HepG2 cells." (PMID 34209205, 2021). "The compound induced AHR targets at the mRNA as well as at the protein level in vitro, even though reporter assays did not reveal a substantial potential in human hepatoma cells." (PMID 32403288, 2020). "Prior to more extensive analysis of the specific interactions of these compounds with the AhR, we first confirmed that 1,2-NQ and 1,4-NQ stimulated induction of the AhR-responsive gene CYP1A1/cyp1a1 in human and mouse hepatoma cells, respectively, in a concentration-dependent manner." (PMID 32526934, 2020). "The documented ability of the AhR antagonist CH223191 to inhibit TCDD- but not IR-dependent gene expression in rat hepatoma cells suggests that these two ligands differentially interact with the AhR LBD." (PMID 30201897, 2018). "SU5416 significantly inhibited proliferation of Hepa1 hepatoma cells in an AhR-dependent manner, but did not induce apoptosis." (PMID 28424418, 2017). "Analyses of seven hepatoma cell lines (Hep G2, Hep 3B, SK-Hep1, Huh 7, PLC/PRF/5, HA22T, and HCC36) revealed that AHR and HDAC8 were highly expressed in all of the hepatoma cell lines as compared with expression levels in normal hepatocytes (Chang normal liver cells, CNL)." (PMID 27283490, 2017). "Specifically, exposure to TCDD did not affect mRNA levels of CTNNB1 target genes Axin2 and Lgr5 in the hepatoma cell line, nor did 3-methylcholanthrene (3MC, an AHR agonist) affect mRNA levels of the same two target genes in the liver." (PMID 25286307, 2014). "While canonical Wnt signaling was found to enhance AHR signaling in vivo in mouse liver and in a mouse hepatoma cell line, activated AHR did not alter canonical Wnt signaling." (PMID 25286307, 2014). "While kynurenine is produced by the tryptophan catabolizing enzyme TDO in several types of cancer including glioma, hepatocellular carcinoma and melanoma to promote immune evasion, we demonstrate here that IDO1 is equally capable of employing the AHR pathway in NSCLC and ovarian carcinoma cells." (PMID 24657910, 2014).
hepatoma (continued). "In a mouse hepatoma cell line, TCDD activated expression of an AHR reporter gene (luciferase driven by a promoter containing three DREs) to a significantly greater extent in cells expressing a stabilized CTNNB1 (CTNNB1S33Y mutation) than in control cells expressing wild type CTNNB1." (PMID 25286307, 2014). "Sucrose density gradients showed that an amount of AhR protein was found in Cav-1-containing DRM fractions of T-FGM AhR+/+ fibroblasts (upper) and, importantly, of phenotypically unrelated mouse Hepa1 hepatoma cells (lower)." (PMID 25238970, 2014). "In this study, we provide evidence that phthalate promotes hepatocellular carcinoma progression through a nongenomic AhR pathway." (PMID 25081364, 2014). "Accordingly, to examine the species specificity of ginsenosides as AHR agonists, we evaluated their ability to induce DRE-luciferase gene expression in stably transfected rat (H4L1.1c4), mouse (H1L1.1c2) and human (HG2L6.1c3) hepatoma cell lines." (PMID 23776647, 2013). "A previous study showed that in murine hepatoma cells, estradiol suppressed the AhR–DRE pathway triggered by dioxin through AhR but not through the ER." (PMID 18335102, 2008). "Introduction of AhR into c12, a similar AhR-defective mouse hepatoma cell line, also did not restore albumin expression, and furthermore, did not lead to changes in cellular morphology or cell cycle parameters." (PMID 19936078, 2007). "Nevertheless, in this study, we conclude that AhR, in the absence of sufficient amounts of exogenous ligands, has little effect on the proliferation or state of differentiation of mouse hepatoma cells." (PMID 19936078, 2007). "Moreover, we have evidence that 3-IAld activates AhR-dependent genes in a human hepatoma cell line in vitro (data not shown)." (PMID 34209524, 2021). "Correspondingly, BBP, inhibiting GJIC and activating MAPK-Erk1/2 in our study, was previously found to induce invasion, migration, and the angiogenesis of hepatocellular carcinoma cells Huh7 via rapid non-genomic aryl hydrocarbon receptor/G-protein dependent mechanism." (PMID 32842520, 2020). "For example, it has been shown that an increase in the cellular pool of another xeno-sensing receptor, the aryl hydrocarbon receptor (AHR), in mouse hepatoma cells does not result in elevated transcription of AHR target genes following stimulation of the cells with an AHR agonist." (PMID 33097968, 2020). "To determine whether AHR activated HDAC8 via a genetic mechanism, we transfected an AHR expression construct into hepatoma cells, and the mRNA and protein levels of HDAC8 were measured by real-time PCR and western blotting, respectively, in AHR-overexpressing cells." (PMID 27283490, 2017). "Furthermore, knockdown of CTNNB1 in two mouse hepatoma cell lines, as well as in vivo knockout of CTNNB1 in mouse hepatocytes, both resulted in a significantly weaker upregulation of Cyp1a1 transcription after activation of AHR." (PMID 25286307, 2014). "Incubation of mouse hepatoma (hepa1c1c7) cells with ginsenosides (Rc, Rh1, PPD, F11) for 4 h increased CYP1A1 mRNA levels, albeit to a lower level than that induced by TCDD, but these data were consistent with the reporter gene induction results and the AhR agonist activity of these ginsenosides." (PMID 23776647, 2013). "This may be the consequence of these genes not being expressed in hepatoma cells, but yet having a poised AHR that may still occupy the promoter at appropriate motif sites without causing changes in transcription." (PMID 19654925, 2009). "Therefore, AhR-mediated dysregulation of the circadian clock may be a unifying mechanism which contributes to the pleiotropic effects of TCDD including hepatotoxicity, wasting syndrome, hepatocellular carcinoma, and gut dysbiosis." (PMID 31015483, 2019). "Previous studies in rat hepatoma (H4IIE), human hepatoma (AZ-AhR) and fish liver (RTL-W1) cell lines reported that DBT induced weak-to-no AhR activity and failed to induce CYP1A activity in EROD assays." (PMID 40869324, 2025).
hepatoma (continued). "Surprisingly, however, the tryptophan photoproduct and non-carcinogenic endogenous AhR ligand FICZ (6 formylindolo[3,2-b]carbazole) induced LINE-1 retrotransposition in human hepatocellular carcinoma HuH-7 cells by a mechanism requiring ARNT and MAPK but not AhR." (PMID 27243009, 2016).